NEDD9 (neural precursor cell expressed, developmentally down-regulated 9)
Diseases named in the same sentence as NEDD9 in open-access papers (continued):
Sharing a sentence is not in itself a finding about the gene and the disease.
neurodegenerative disease (2 papers, 2014 to 2023). A disorder of the central nervous system characterized by gradual and progressive loss of neural tissue and neurologic function. "In humans, polymorphisms in the NEDD9 gene have been associated with neurodegenerative diseases, including Alzheimer’s and Parkinson’s disease." (PMID 37863893, 2023). "To date, although PTK2B and NEDD9 are abundant in neurites, a PTK2B-NEDD9-AURKA-NDEL1 axis has not been considered in neurite extension or neurodegenerative diseases." (PMID 25594051, 2014).
bacterial infection (1 paper, 2025). "AKT is recognized as a general regulator of lysosomal function associated with bacterial infections and beyond, and is also a known downstream target of NEDD9." (PMID 40506423, 2025). "In order to further elucidate the role of NEDD9 upon bacterial infection of macrophages, we infected mBMDMs with ST and analyzed NEDD9 protein levels by Western Blot analysis and immunofluorescence microscopy at timpoints 0.25, 0.5, 1, 4 and 24 hours." (PMID 40506423, 2025). "Our study has thus identified NEDD9 as a critical regulator of lysosomal function in macrophages and a potential host-directed therapeutic target to treat bacterial infections." (PMID 40506423, 2025). "Bacterial infections induced host-mediated lysosomal degradation of NEDD9 in macrophages and PBMCs isolated from patients suffering from bloodstream infection." (PMID 40506423, 2025). "To understand the mechanism of NEDD9 downregulation in macrophages during bacterial infection, we analyzed whether the depletion of NEDD9 protein occurs by proteasomal degradation, as previously reported for other stimuli." (PMID 40506423, 2025). "Furthermore, it indicates that downregulation of NEDD9 facilitates phagolysosomal activity in macrophages upon bacterial infection." (PMID 40506423, 2025). "In conclusion, our results suggest that downregulation of NEDD9 is a host defense mechanism that could serve as a potential host-directed target to treat bacterial infection (graphical abstract)." (PMID 40506423, 2025).
CNS tumours (1 paper, 2012). "To assess the gene expression profile of hypoxia-induced genes in brain and CNS tumours, we queried the oncomine database for the following genes; HIF1A1, VEGFA, MMP2, NEDD9, SOX4, and SOX9." (PMID 22570651, 2012).
neurological diseases (1 paper, 2014). "Among them, Nptx2, Nedd9, Rorb, Cux2, and Htr3a are involved in neuronal development or associated with neurological diseases." (PMID 25071448, 2014).
NEDD9 also shares sentences with these, for which no sentence is quoted: head and neck squamous cell carcinoma (3 papers); oral squamous cell carcinoma (3); ovarian carcinoma (3); acute myeloid leukaemia (2); brain disorder (2); breast invasive carcinoma (2); endometrial cancer (2); late-onset Alzheimers disease (2); leukemia (2); mesothelioma (2); osteosarcoma (2); rheumatoid arthritis (2); asthma (1); autism (1); benign melanocytic nevus (1); bladder (1); chronic myelogenous leukemia (1); colorectal tumors (1); cutaneous melanoma (1); depression (1); fibrosis (1); gastric adenocarcinoma (1); gastrointestinal stromal tumor (1); gynecological cancers (1); head and neck cancer (1); HTLV infection (1); liver cancer (1); liver cirrhosis (1); malignant mesothelioma (1); metastatic prostate carcinoma (1).
A further 15 diseases each share a sentence with NEDD9 in 1 paper.